CXCR4 (C-X-C motif chemokine receptor 4)
Diseases named in the same sentence as CXCR4 in open-access papers (continued):
Sharing a sentence is not in itself a finding about the gene and the disease.
cancer (continued). "In the flow cytometric analysis, the signal for cell surface CXCR4 of the metastasized cancer cells was remarkably reduced compared with that of the cancer cells in the orthotopic tumors." (PMID 26083776, 2015). "MMP-2 degrades the extracellular matrix, which promotes cancer cell invasion, and we previousl found that CXCR4 promoted human cancer cell invasion by upregulating MMP-2." (PMID 26213494, 2015). "Evaluating possible underlying mechanisms revealed a strong downregulation of CXCR4, the receptor for the chemokine SDF-1 important for homing of cancers cells to the bone." (PMID 25909161, 2015). "On the other hand, the convergence of the CXCL12/CXCR4 axis in several studies of multiple tumors suggested the use of CXCR4 inhibitors in the treatment of cancer." (PMID 26062132, 2015). "M210B4 cells express high levels of SDF-1 protein and can stimulate the adhesion and migration of CXCR4-expressing cancer cells." (PMID 26652601, 2015). "We showed that the peripheral nerve-derived CXCL12 stimulated the invasion and chemotactic migration of CXCR4-positive cancer cells in a paracrine manner, eventually leading to PNI." (PMID 25605248, 2015). "Single-cell multiplex gene expression analysis of the xenograft tumors revealed the downregulation of the chemokine receptor CXCR4 in the dormant cancer cells." (PMID 26083776, 2015). "XN suppresses CXCR4 expression in cancer cells at the transcriptional level via blocking endogenous activation of NFκB, which regulates the expression of CXCR4 in cancer cells." (PMID 25574819, 2015). "SDF-1 has been found to exert an inhibitory function on cancer apoptosis by binding with its primary receptor CXCR4, which is a seven transmembrane G-protein coupled receptor." (PMID 25909286, 2015). "Despite the fundamental role of CXCR4 in cancer and in particular MM biology and its significance as a target for therapeutic approaches, a highly sensitive method for CXCR4 assessment and quantification in vivo has been lacking so far." (PMID 25736399, 2015). "CXCR4 is a major chemokine receptor and is expressed in multiple types of cancer, such as breast and prostate." (PMID 26622806, 2015). "In this study, the metastatic cancer cells showed a lower expression level of CXCR4 than the cells in the orthotopic tumors." (PMID 26083776, 2015). "Western Blot analysis confirmed that cancer cell lines, that are known to have an invasive phenotype, have a higher expression of CXCR4 (45-47 kDa)." (PMID 26396176, 2015). "CXCL12 and its receptor chemokine (CXC motif) receptor-4 (CXCR4) play a role in migration of hematopoietic stem cells and cancer cells." (PMID 29061949, 2015). "Extracellular ubiquitin has chemotactic properties inducing the migration of different cancer cell types as well as THP1 cells via CXCR4, PLC, AKT, and the MEK/ERK pathway." (PMID 26347749, 2015). "It is possible that the high level of immunostaining of SDF-1 in cancer cells resulted from accumulation of secreted SDF-1 by stromal cells through SDF-1/CXCR4 interaction." (PMID 26296527, 2015). "The mice in the sh-CXCR4 group began to experience hind-limb dysfunction 10-15 days after cancer cell injection and developed left hind limb paralysis in the 6th week." (PMID 25605248, 2015). "In fact, blockade of CXCR4 only partially inhibited migration of cancer cells to CXCL12 gradients in vivo because the relationship between CXCR7 (the secondary receptor of CXCL12) and CXCR3 via their shared ligand CXCL11 has made this interaction more complex." (PMID 26062132, 2015). "In the ex vivo culture, the expression levels of CXCR4 in the orthotopic cancer cells were markedly reduced in both low (70–80% confluent) and high (100% confluent) cell densities." (PMID 26083776, 2015). "CXCR4 is a target for novel cancer therapies and small molecule inhibitors of CXCR4, such as plerixafor (AMD3100), are being investigated clinically in various cancers." (PMID 25978616, 2015).
cancer (continued). "The chemokine receptor CXCR4 has been shown to mediate cellular functions such as proliferation, migration, invasion, and adhesion in a variety of cancer types." (PMID 26560447, 2015). "More importantly, CXCR4 overexpression has been detected in at least 23 different types of human cancer." (PMID 25997540, 2015). "Although CXCR4 overexpression has been reported in several human cancers, this is the first study to reveal CXCR4 is closely related to the CSC phenotypes of diffuse-type GC that has a high PD ability." (PMID 26110809, 2015). "We highlight the importance of CXCL12-γ in cancer cell migration: its high effective affinity for both extracellular surface sites and CXCR4 strongly promote CXCR4+ cell migration." (PMID 25909600, 2015). "The chemokine/chemokine receptor axis SDF-1alpha/CXCR4 is a major determinant for recruiting cancer cells to this protective niche." (PMID 25736399, 2015). "CXCR7 is another receptor for CXCL12 with rather high binding affinity and is reported to be involved in cancer cell proliferation in a CXCR4-independent and/or-dependent manner." (PMID 26083776, 2015). "Some of these cancer-related genes were associated with processes occurring in the extracellular matrix and related to DCN: CXCR4/CXCL12 axis, SELP, vWF, COL3A1, SCARA, SPARCL1." (PMID 26437222, 2015). "vMIP-II-derived peptides are also being investigated as CXCR4 inhibitors in the context of cancer therapy." (PMID 26347749, 2015). "Some CXCR4 antagonists have even been tested in clinical studies with the aim to treat different kinds of cancers (e.g., hematological cancers and brain tumors)." (PMID 25671300, 2015). "A wide variety of potential drugs targeting CXCL12/CXCR4 and downstream signaling pathways, including peptides, small molecules, antibodies, and small interfering RNA, have been tested for cancer therapy." (PMID 26176534, 2015). "CXCL12 derived from the peripheral nerves stimulated the invasion and chemotactic migration of CXCR4-positive cancer cells in a paracrine manner, eventually leading to PNI." (PMID 25605248, 2015). "Expression and activation of CXCR4 has been shown to positively regulate several developmental and oncogenic signaling pathways in many cancer types." (PMID 25775124, 2015). "Inhibition of CXCR4 effectively blocked cancer progression in vitro through the traditional Wnt pathway in a previous study." (PMID 26622806, 2015). "Another in vivo model was performed to explore the effect of CXCR4-silencing in cancer cells on their invasion along nerves." (PMID 25605248, 2015). "Our findings suggest that it will be productive to evaluate the CD26/CD44/CD133/CXCR4 status of refractory cancer cells in future studies of CRC." (PMID 26552750, 2015). "On the other hand, previous reports suggested that anticancer agents induce the expression of CXCR4 in cancer cells." (PMID 26083776, 2015). "In this manuscript we took advantage of the NCI 60 cell lines to investigate the level of two putative cancer stem cell markers, CXCR4 and CD133." (PMID 26020117, 2015). "Colon (HT29) and breast (MDA-MB231) cancer cells expressing CXCR4 were studied in vitro and in xenograft tumors propagated in severe combined immunodeficient mice." (PMID 26318034, 2015). "In patients with various types of cancer, PDMPs possess CXCR4 and contribute to chemotaxis by stromal cell-derived factor 1, resulting in progression or metastasis of cancer." (PMID 25705427, 2015). "Further investigations were needed to clarify the role of CXCR4 as a biomarker for prognosis in these types of cancer." (PMID 25669980, 2015). "Certain chemokines and their receptors, in particular SDF-1 α and CXCR4, are expressed in various epithelial cancer cells and favor cancer cell migration, proliferation, and survival." (PMID 26318034, 2015). "The accumulating reports have shown that CXCL12 and CXCR4 are overexpressed both in mRNA and protein levels during initiation and progression of cancers." (PMID 26078947, 2015).
cancer (continued). "A majority of cancer cells and nerve tissues showed distinct immunostaining of CXCR4 and CXCL12 localized to the cytoplasm." (PMID 25605248, 2015). "Previous studies had indicated that CXCR4 was involved in the vascularization and metastasis of cancer." (PMID 26526157, 2015). "Here eighty-five studies with a total of 11,032 subjects were included to explore the association between CXCR4 and progression-free survival (PFS) or overall survival (OS) in subjects with cancer." (PMID 25669980, 2015). "Interferon-γ reduced CXCR4 expression on cancer cells and inhibited the CXCL12-induced cell migration." (PMID 25609202, 2015). "Continuing with the parameters relevant to receptor overexpression in cancer, we allowed CXCR4+ cells to move." (PMID 25909600, 2015). "Relative cancer cell CXCR4 expression in these patients was high compared to intraindividual control BM cell populations." (PMID 25736399, 2015). "As CXCR4 is overexpressed in several human cancers, the blockade of CXCR4–CXCL12 interaction represents from many years an interesting drug-target." (PMID 26030674, 2015). "CXCL12 primarily binds to CXCR4 and induces intracellular signaling through several divergent pathways, which are involved in progression and metastasis of cancer." (PMID 26078947, 2015). "Our study shows that the expression of CXCR4 is a significant and independent biomarker of worse prognosis in cancer." (PMID 25669980, 2015). "Although the SDF-1α-CXCR4 and SDF-1α-CXCR7 axes were each involved in cancer cell survival we showed here that 1 / CXCR4 is the main represented receptor for the α-chemokine SDF-1α on MiaPaCa-2 cell membranes." (PMID 25821841, 2015). "Then we analyzed the effect of the inhibition of the CXCR4 signaling on dormancy of the metastasized cancer cells in the lung." (PMID 26083776, 2015). "Our data provides evidence that IL-24 in combination with CXCR4 inhibitors will be more effective in controlling cancer metastasis." (PMID 25775124, 2015). "The chemokine CXCL12 (SDF-1) and its receptor CXCR4 were shown to play a key role in regulating the trafficking of cancer cells to sites of metastases." (PMID 25949860, 2015). "CD133 and CXCR4 were evaluated in the NCI-60 cell lines to identify cancer stem cell rich populations." (PMID 26020117, 2015). "Intriguingly, we found that the PCa cell lines rarely expressed CXCL12, but the majority of cancer cells surrounding or infiltrating in nerves showed distinct immunostaining of CXCR4 and CXCL12." (PMID 25605248, 2015). "C-X-C chemokine receptor 4 (CXCR4) is believed to be one key factor in the cross-talking between cancer cells and its microenvironment, what makes it a very promising prognostic biomarker and target for cancer therapy." (PMID 25669980, 2015). "In contrast, the expression level of CXCR4 was markedly increased in the ex vivo cultured cancer cells obtained from the lung, and eventually reached almost the same level as that of the cells from the orthotopic tumors." (PMID 26083776, 2015). "Previous studies have shown that CXCR4, VEGF, TGF-β, ICAM-1 are associated with various roles of macrophages during the process of carcinoma invasion and metastasis." (PMID 25434400, 2015). "Because CXCR4 was strongly expressed in highly proliferative G3 carcinomas, it is an interesting new target and needs to be validated in larger studies." (PMID 26259237, 2015). "Because CXCR4 was strongly expressed in highly proliferative G3 carcinomas, we believe that CXCR4 is an interesting new target that needs to be validated in larger studies." (PMID 26259237, 2015). "When CXCR4 is expressed on the surface of carcinoma cells, CAFs can directly enhance the proliferation of these cells via an SDF-1/CXCR4 paracrine loop." (PMID 25774287, 2015). "CXCR4 is over-expressed in more than 20 different cancers, and expression in normal tissues (other than in the CD34 stem cell niche in bone marrow) is measurably lower." (PMID 24959420, 2014).
cancer (continued). "In monocytes, an increase in CXCR4 expression has been shown in CD14+CD16− cells cultured with cancer cells, alongside increases in the expression of CCR2, CXCR1 and CXCR2." (PMID 25251539, 2014). "While CXCL12/CXCR4 activation within both cancer cells and local stroma clearly contributes to GBM cell proliferation, spreading, and survival to therapy, more recent studies demonstrated that CXCR7 is an alternative, or additional, regulator of GBM growth." (PMID 24904289, 2014). "RGS16 has been implicated in negatively regulating the MAPK, AKT/PI3K, RhoA, and SDF-1/CXCR4 oncogene pathways in normal or cancer cell lines." (PMID 25568667, 2014). "In the network of chemokine signaling pathways, recent reports have described the SDF-1α/CXCR4 axis and its role in cancer progression and metastasis." (PMID 25114911, 2014). "The CXCL12/CXCR4 axis has been shown to promote cell survival by inhibiting apoptosis in cancer cells; thus, CTCE-9908-mediated inhibition of the CXCL12/CXCR4 pathway leads to loss of protection from apoptosis and increased cell death." (PMID 24472670, 2014). "Directed metastasis of cancer cells is mediated by CXCR4 activation and migration of cancer cells towards CXCL12 expressing organs." (PMID 24658065, 2014). "Prevailing data on CXCR4 expression in several types of cancer were obtained by immunohistochemistry; however, the commonly used anti-CXCR4 antibody is only able to recognize a subpopulation of CXCR4 molecules." (PMID 24765189, 2014). "Small molecule CXCR4 inhibitors are intensively being studied as mobilizers of hematopoietic stem cells for transplantation therapy of patients with specific types of cancer." (PMID 24966838, 2014). "The authors cited disruption of SDF-1/CXCR4 signaling in the metastasis of stem-like cancer cells by a PPARγ dependent mechanism as a possible new cancer control treatment." (PMID 25191225, 2014). "While other GPCR family members are overexpressed in few specific cancers, CXCR4 is overexpressed in more than 23 different types of cancer." (PMID 25514788, 2014). "Patients who had CXCR4 overexpression had significantly higher incidence of cancer recurrence and cancer-related deaths than those in low CXCR4 expression group." (PMID 24591761, 2014). "In this study, we have demonstrated that the blockade of CXCR4 can decrease IHCC cancer cell growth and cell cycle by prolonging the G0–G1 cycle and reducing the G2 and S phases, and inhibit tumorigenesis both in vitro and in vivo." (PMID 25471741, 2014). "The IRS of the cancer cells with membranous CXCR4 expression ranged from 1 to 12 (median 6.1), with 11/28 (39.3%) cases considered positive." (PMID 25240521, 2014). "Meanwhile, CXCL12 and CXCR4 were found to be instrumental for the development and progression of numerous different cancer types of epithelial, haematopoietic or mesenchymal origin." (PMID 24390633, 2014). "CXCR4 induction is one of the identified mechanisms for the growth factor control in cancer cells, which supports the migration of cancer cells." (PMID 24906407, 2014). "This recruitment mimics the homing of normal stem cells to the bone marrow, and cancer cells homed to bone marrow reside in a microenvironment that protects them in a CXCR4-dependent manner from chemotherapy." (PMID 25471741, 2014). "In this study, cell-matrix adhesion and wound-healing assays were performed to determine the impact of CXCR4-shRNA on cancer cell adhesion and migration." (PMID 25202367, 2014). "CXCR4 has been reported to be upregulated in more than 20 cancers, including ovarian, prostate, esophageal, melanoma, neuroblastoma, and renal cell carcinoma, and plays an important role in the communication of cancer cells with their microenvironment." (PMID 25471741, 2014). "Recent studies also show a role of the CXCR4/CXCL12 axis in triggering interaction of cancer cells with microvascular endothelial cells and GBM cancer stem cell transdifferentiation into pericytes." (PMID 24662753, 2014).
cancer (continued). "It is well established that CXCR4+ cancers metastasize to the distant organs in a CXCL12/SDF-1-dependent manner." (PMID 24674692, 2014). "The chemokine SDF-1 and its receptors, CXCR4 and CXCR7, have been implicated in cancer progression and metastasis." (PMID 24765189, 2014). "The role of CXCR7 in cancer progression cannot be ignored, but distinguishing between the effects of CXCR4 and CXCR7 signalling will be difficult." (PMID 24583601, 2014). "Our study also showed that in various adherent cancer cell lines, CXCR4 surface expression increased when grown as 3D spheroids." (PMID 25514788, 2014). "In various types of cancer, CXCR4 plays a vital role in tumorigenesis and the progression of cancer." (PMID 24475985, 2014). "In other words, we propose that the opposite action of COUP-TFI on CXCL12 and CXCR4 expression enhances the migration capacity of cancer cells through an increase in sensitivity to exogenous CXCL12 and by limiting the autocrine retention effect of CXCL12." (PMID 24906407, 2014). "Although the pivotal role of the CXCL12/CXCR4 axis in cell motility and consequently in cancer metastasis in several tissues is well established, the contribution of CXCL12 via its receptor CXCR7 is less understood." (PMID 24906407, 2014). "Elevated levels of validated miR-133b targets such as CXCR4, FGFR1, FSCN1 has been associated with prognosis of various cancers." (PMID 24967583, 2014). "MMP-9 is a downstream signaling molecule of CXCR4 and is critical for the migration and invasion of cancer cells." (PMID 24765179, 2014). "RGS16 was of interest to our study for two reasons: 1) RGS16 regulates GPCRs, which are common targets for deregulation in cancer and 2) RGS16 has been linked to regulating the MAPK/RAS, PI3K/AKT, RhoA, and SDF-1/CxCR4 oncogene pathways." (PMID 25568667, 2014). "CXCR4-positive cancers metastasize to the lymph nodes, liver, and bones in a CXCL12-dependent manner." (PMID 24647809, 2014). "As a result of both treatments, ECFCs invasion was strongly impaired, thus indicating that ECFCs were recruited in vitro by SDF1 released by MSCs and also by cancer cells, as demonstrated by the inhibition of CXCR4/SDF1 in the co-colture experiments." (PMID 25003596, 2014). "It is known, that CXCR4 expression can be enhanced by additional factors, such as hipoxia, wich up-regulates CXCR4 expression on cancer cells." (PMID 24859274, 2014). "CXCR4 (over)expression has been detected in CSCs derived from various of cancer histotypes, including pancreatic, colon, lung, breast prostate, renal, and GBM." (PMID 24904289, 2014). "The conventional paradigm for chemokine mediated metastasis of cancer cells is that expression of CXCR4 is pro-metastatic." (PMID 24594697, 2014). "CXCR4 is seven-transmembrane, G protein-coupled receptor that is found to be expressed in many human cancer cells." (PMID 24941119, 2014). "The CXC chemokine ligand-12 (CXCL12)/CXC chemokine receptor type 4 (CXCR4) axis has been shown to be involved in tumorgenesis, proliferation, and angiogenesis in a variety of cancers including IHCC." (PMID 25471741, 2014). "CXCR4 is a seven-transmembrane, G protein-coupled receptors that is found to be expressed in many human cancer cells." (PMID 24941119, 2014). "In previous reports, CXCR4 expression was found in nucleus, cytoplasm, and membrane of diverse cancer cells by means of immunohistochemistry." (PMID 24658065, 2014). "Stromal cell-derived factor-1 (SDF-1 or CXCL12) and its unique receptor CXCR4 have prominent roles in chemotaxis and metastasis of a diverse number of cancers." (PMID 24941119, 2014). "ERG triggered the migratory potential of cancer cells by the overexpression of CXCR4 and ADAM metallopeptidase with a thrombospondin type 1 motif, 1 (ADAMTS1) as ChIP assay demonstrated direct binding of ERG to the promoter region for both CXCR4 and ADAMTS1." (PMID 24739220, 2014).